SLC43A3 (solute carrier family 43 member 3)
Description:
Sodium-independent purine-selective nucleobase transporter which mediates the equilibrative transport of extracellular purine nucleobases such as adenine, guanine and hypoxanthine. May regulate fatty acid (FA) transport in adipocytes, acting as a positive regulator of FA efflux and as a negative regulator of FA uptake (By similarity). [Isoform 1]: Sodium-independent purine-selective nucleobase transporter which mediates the equilibrative transport of extracellular purine nucleobase adenine. Mediates the influx and efflux of the purine nucleobase analog drug 6-mercaptopurine across the membrane. [Isoform 2]: Sodium-independent purine-selective nucleobase transporter which mediates the equilibrative transport of extracellular purine nucleobase adenine. Mediates the influx and efflux of the purine nucleobase analog drug 6-mercaptopurine across the membrane.
Synonyms: ENBT1; SEEEG-1; Eeg1; DKFZp762A227; FOAP-13; PRO1659
Tractability: Antibody: UniProt places it where antibodies can reach, with high confidence; UniProt predicts a signal peptide or a membrane-spanning region; its Gene Ontology location is reachable by antibodies, with medium confidence; the Human Protein Atlas places it where antibodies can reach. PROTAC: ubiquitination databases record sites on it; its protein half-life has been measured.
Gene: Protein-coding gene on chromosome 11 (57,406,954 to 57,429,035, reverse strand). Ensembl gene ENSG00000134802.
Subcellular location: Basolateral cell membrane
Subcellular location (Human Protein Atlas): Vesicles; Nucleoplasm; Plasma membrane
Gene Ontology:
Molecular function: adenine transmembrane transporter activity; guanine transmembrane transporter activity; protein binding; xenobiotic transmembrane transporter activity; fatty acid transmembrane transporter activity
Biological process: hypoxanthine transport; adenine transport; fatty acid transport; guanine transmembrane transport; xenobiotic transport
Cellular component: basolateral plasma membrane
Genetic constraint (gnomAD): Loss-of-function variants: 31 observed, 52.04 expected, observed/expected ratio (o/e) 0.6, 90% interval 0.45 to 0.8. The upper end of that interval is the gene's LOEUF score, 0.8, which puts it in group 3 of 6, group 1 being the genes least tolerant of losing a copy. Missense variants: 495 observed, 581.92 expected, observed/expected ratio (o/e) 0.85, 90% interval 0.79 to 0.92. Synonymous variants: 222 observed, 240.13 expected, observed/expected ratio (o/e) 0.92, 90% interval 0.83 to 1.03.
Homologues: Orthologues: chimpanzee SLC43A3 (99% identical), macaque SLC43A3 (97% identical), dog SLC43A3 (82% identical), rabbit SLC43A3 (82% identical), pig SLC43A3 (79% identical), rat Slc43a3 (75% identical), mouse Slc43a3 (74% identical), zebrafish slc43a3b (57% identical), zebrafish slc43a3a (54% identical).
Diseases named in the same sentence as SLC43A3 in open-access papers:
SLC43A3 is named in the same sentence as 19 diseases in open-access papers, as found by Europe PMC text mining. Sharing a sentence is not in itself a finding about the gene and the disease. The quoted sentences say what the papers report.
angiosarcoma (4 papers, 2017 to 2024). A malignant tumor arising from the endothelial cells of the blood vessels. "SLC43A3 a novel fusion gene NUP160–SLC43A3 was revealed to be overexpressed in angiosarcoma specimens." (PMID 38705513, 2024).
glioma (4 papers, 2023 to 2025). A benign or malignant brain and spinal cord tumor that arises from glial cells (astrocytes, oligodendrocytes, ependymal cells). "Prognostic analysis using multiple glioma datasets revealed that high expression of SLC43A3 was associated with worse overall survival." (PMID 38378721, 2024). "Using a machine learning framework consisting of LASSO, RSF, XgBoost, Enet, CoxBoost, and Boruta, the authors identified seven RCD genes as potential therapeutic targets in glioma, including SLC43A3, which is highly expressed in gliomas." (PMID 40002166, 2025). "To validate the findings, we assessed SLC43A3 expression in high-grade gliomas compared to normal brain cortex using qRT-PCR." (PMID 38378721, 2024). "Meta-analysis and multiple variate Cox regression analysis provided strong evidence that SLC43A3 was a risky and independent prognostic factor for predicting glioma patients’ outcomes." (PMID 38378721, 2024). "Among these, the role of SLC43A3 in tumors, especially gliomas, had hardly been reported, while the functions of the other genes in tumors were widely documented." (PMID 38378721, 2024). "Our focused investigation on SLC43A3 revealed a RCD-related oncogenic potential in glioma through systematic analysis of its expression profile and prognostic value in multiple datasets and qRT-PCR experiments." (PMID 38378721, 2024). "Immunohistochemical staining of glioma tissue and normal brain tissue also confirmed the significant overexpression of SLC43A3 in gliomas." (PMID 38687049, 2024). "Using the machine learning framework consisting of Lasso, RSF, XgBoost, Enet, CoxBoost and Boruta, we identified seven RCD genes as potential therapeutic targets in glioma and verified that the SLC43A3 highly expressed in glioma grades and glioma cell lines through qRT-PCR." (PMID 38378721, 2024). "Additionally, Kaplan–Meier survival analyses conducted on three distinct datasets, including TCGA pan‐glioma, CGGA325 and CGGA693, further indicate that high expression of SLC43A3 is an adverse prognostic factor." (PMID 38687049, 2024).
acute lymphoblastic leukemia (2 papers, 2024). Leukemia with an acute onset, characterized by the presence of lymphoblasts in the bone marrow and the peripheral blood. "Also, another study found that SLC43A3-encoded equilibration nucleobase transporter 1 (ENBT1) is responsible for importing 6-mercaptopurine, an agent used for the treatment of acute lymphoblastic leukemia, into leukemia cells." (PMID 38705513, 2024).
atherosclerosis (2 papers, 2011 to 2022). A disease characterized by the build-up of fatty material and calcium deposition in the arterial wall resulting in partial or complete occlusion of the arterial lumen. "One studies have shown that after in vitro and in vivo injection of endotoxin and LPS, six candidate genes (BATF, BID, C3aR1, IL1RN, SEC61B and SLC43A3) were identified to be associated with inflammation and atherosclerosis." (PMID 36303246, 2022). "The role of BID, SEC61B, SLC43A3 in atherosclerosis is not yet established." (PMID 21827714, 2011).
glioblastoma (2 papers, 2024). The most malignant astrocytic tumor (WHO grade IV). "Interestingly, the expression of SLC43A3 increased with the pathological grade and was most highly expressed in the ME transcriptional subgroup, which has been associated with a malignant process and shorter median survival time in glioblastoma patients." (PMID 38378721, 2024). "Subsequently, knockdown and overexpression experiments validated that SLC43A3 promotes glioblastoma cell proliferation and migration." (PMID 38687049, 2024). "Given the predominant weight of SLC43A3 in determining SLC expression patterns, we further explored the role of SLC43A3 in glioblastoma." (PMID 38687049, 2024). "In conclusion, we have provided a novel framework for screening important features, identified seven potential important therapeutic targets, and presented solid evidence supporting an oncogenic role of RCD-related SLC43A3 in glioblastoma." (PMID 38378721, 2024). "To further investigate the role of SLC43A3 in glioblastoma, we initially assessed SLC43A3 expression at both mRNA and protein levels in glioblastoma cell lines and clinical samples, confirming high SLC43A3 expression in tumour tissues." (PMID 38687049, 2024). "Transcriptomic data from the CCLE project showed higher mRNA levels of SLC43A3 in most glioblastoma cells compared to LGG cells (H4)." (PMID 38378721, 2024). "The qRT-PCR experiment with glioblastoma cell lines further confirmed higher expression of SLC43A3 in glioblastoma cell lines compared to astrocyte cell lines." (PMID 38378721, 2024). "Finally, we demonstrated the oncogenic role of the orphan protein SLC43A3 in glioblastoma, suggesting its potential as a novel therapeutic target." (PMID 38687049, 2024). "Finally, we substantiated the crucial role of the model's core member, SLC43A3, in promoting the malignant phenotypes of glioblastoma cells, including proliferation and migration through molecular biology experiments." (PMID 38687049, 2024). "This suggests that SLC43A3 may function as an oncogene in glioblastoma and could potentially serve as a novel therapeutic target for glioblastoma treatment in the future." (PMID 38687049, 2024).
leukaemia (2 papers, 2023 to 2024). "In terms of the leukemia cell lines tested, MOLT-4 cells express the SLC43A3 transcript and L1210 cells express the slc43a3 transcript, confirming primer species specificity." (PMID 39361655, 2024).
asthma (1 paper, 2020). "Concretely, four genes (ATF7IP, SLC43A3, AKAP7, HMGN1) were found to be correlated to pathogenesis or treatment of asthma in immune." (PMID 32948203, 2020).
disc degeneration (1 paper, 2024). "T2-weighted MR images demonstrated lower Pfirrmann scores in the PA group than in the control group, indicating severe disc degeneration, but the scores were significantly increased after the model rats were treated with SLC43A3." (PMID 38714886, 2024). "In addition, the expression of SLC43A3 was negatively correlated with disc degeneration grade (r = −0.85, P < 0.001) and TG content (r = −0.79, P < 0.001)." (PMID 38714886, 2024). "Moreover, validation with data obtained from a large-cohort sample showed that SLC43A3 expression levels were negatively correlated with lipid content and disc degeneration grade." (PMID 38714886, 2024).
endometriosis (1 paper, 2016). The growth of functional endometrial tissue in anatomic sites outside the uterine body. "SLC43A3 is expressed during embryogenesis but the possible role in endometrium or endometriosis development remains to be elucidated." (PMID 26759613, 2016).
lung carcinoma (1 paper, 2024). "Orphan SLC protein SLC43A3 has been relatively understudied and was previously reported to be associated with fatty acid and purine metabolism, serving as a biomarker for chemotherapy effectiveness in lung cancer." (PMID 38687049, 2024).
pulmonary diseases (1 paper, 2021). "For example, CLP1 is linked to cardiac muscle hypertrophy, YPEL4 has a role in pulmonary diseases, P2RX3 and ENSGALG00000007381 are involved in blood coagulation (Reactome; Uniprot), and SLC43A3 plays a possible important role in the repair and growth of the lung tissue under oxidative stress." (PMID 34021753, 2021).
cancer (6 papers, 2012 to 2025). A tumor composed of atypical neoplastic, often pleomorphic cells that invade other tissues. "Thirdly, although we identified seven candidate genes for therapy, we only validated the expression profile of SLC43A3 in tissues and cancer cell lines using qRT-PCR." (PMID 38378721, 2024). "Interestingly, certain repressed genes like B4GALT2, ELANE, CTSG, MLC1, NMP3, and SLC43A3 act as cancer suppressors, inhibiting malignant features and cancer development." (PMID 40986633, 2025). "Furthermore, the orphan protein SLC43A3, a core member of the 7‐SLC classification system, was identified as a key facilitator of tumour cell proliferation and migration, suggesting its potential as a novel target for cancer therapy." (PMID 38687049, 2024).
tumor (2 papers, 2012 to 2024). "The results revealed a significant enrichment of signalling pathways associated with tumour progression, such as PI3K‐Akt and JAK–STAT, in the high SLC43A3 expression group." (PMID 38687049, 2024). "Edu experiments provided additional evidence, confirming a distinct suppression in the proliferation of tumour cells after SLC43A3 downregulation." (PMID 38687049, 2024). "The migratory capacity of tumour cells was markedly hindered after the downregulation of SLC43A3." (PMID 38687049, 2024). "Lastly, whether the impact of SLC43A3 on tumour cell proliferation and migration is related to the PI3K‐AKT signalling pathway requires further experimental confirmation." (PMID 38687049, 2024). "The results indicate that SLC43A3, SLC25A43, SLC2A10 and SLC47A1 show sporadic expression in both tumour cells and TAMs." (PMID 38687049, 2024). "For CA12, GALNT7, LMO3, and SLC43A3 there is good separation in expression between tumor and normal tissue at each dose level as well as a suggestion of opposing trends with dose." (PMID 22848350, 2012). "Interestingly, similar to the results obtained from bulk analysis, the single‐cell data showed a higher detection of SLC43A3, SLC2A10, SLC25A43, SLC7A7 and SLC47A1, which are highly expressed in tumour tissues, relative to SLC1A6 and SLC24A4, which are lowly expressed." (PMID 38687049, 2024). "The results demonstrated significantly higher expression of SLC43A3 and SLC2A10 in tumour slices compared to adjacent non‐cancerous tissue slice, with almost no detectable expression of SLC1A6 in the tumour slices." (PMID 38687049, 2024).
SLC43A3 also shares sentences with these, for which no sentence is quoted: thyroid cancer (2 papers); chronic myeloid leukemia (1); colorectal cancer (1); lymphoma (1); neuroblastoma (1); prostate carcinoma (1).